SPMIP5 (sperm microtubule inner protein 5)
Description:
Microtubule inner protein (MIP) part of the dynein-decorated doublet microtubules (DMTs) in flagellum axoneme. May serve to reinforce and thus stabilize the microtubule structure in the sperm flagella.
Synonyms: C10orf82; MGC33547; Em:AC016825.4
Tractability: No criterion of Open Targets' tractability assessment is met for any kind of drug.
Gene: Protein-coding gene on chromosome 10 (116,662,208 to 116,670,312, reverse strand). Ensembl gene ENSG00000165863.
Subcellular location: Cytoplasm, cytoskeleton, flagellum axoneme; Cytoplasm; Nucleus
Subcellular location (Human Protein Atlas): Mitochondria
Gene Ontology:
Cellular component: cytoplasm; nucleus
Genetic constraint (gnomAD): Loss-of-function variants: 18 observed, 23.16 expected, observed/expected ratio (o/e) 0.78, 90% interval 0.54 to 1.15. The upper end of that interval is the gene's LOEUF score, 1.15, which puts it in group 5 of 6, group 1 being the genes least tolerant of losing a copy. Missense variants: 265 observed, 296.58 expected, observed/expected ratio (o/e) 0.89, 90% interval 0.81 to 0.99. Synonymous variants: 106 observed, 119.19 expected, observed/expected ratio (o/e) 0.89, 90% interval 0.76 to 1.04.
Homologues: Orthologues: chimpanzee SPMIP5 (98% identical), macaque SPMIP5 (93% identical), rabbit SPMIP5 (71% identical), dog SPMIP5 (70% identical), guinea pig SPMIP5 (65% identical), mouse Spmip5 (61% identical), rat Spmip5 (57% identical).
Diseases named in the same sentence as SPMIP5 in open-access papers:
SPMIP5 is named in the same sentence as 4 diseases in open-access papers, as found by Europe PMC text mining. Sharing a sentence is not in itself a finding about the gene and the disease.
SPMIP5 shares sentences with these, for which no sentence is quoted: leukemia (1 paper); ovarian carcinoma (1); prostate carcinoma (1); T-cell leukemia (1).